MAZ (MYC associated zinc finger protein)
Description:
Transcriptional regulator, potentially with dual roles in transcription initiation and termination. [Isoform 1]: Binds DNA and functions as a transcriptional activator. Binds to two G/A-rich sites, ME1a1 and ME1a2, within the MYC promoter having greater affinity for the former. Also binds to multiple G/C-rich sites within the promoter of the Sp1 family of transcription factors. [Isoform 2]: Binds DNA and functions as a transcriptional activator. Inhibits MAZ isoform 1-mediated transcription. [Isoform 3]: Binds DNA and functions as a transcriptional activator.
Synonyms: SAF-1; ZNF801; ZF87; Pur-1; Zif87; PUR1; SAF-2; SAF-3
Tractability: PROTAC: ubiquitination databases record sites on it; its protein half-life has been measured.
Gene: Protein-coding gene on chromosome 16 (29,806,106 to 29,811,164, forward strand). Ensembl gene ENSG00000103495.
Subcellular location: Nucleus
Subcellular location (Human Protein Atlas): Nucleoplasm
Gene Ontology:
Molecular function: DNA-binding transcription factor activity, RNA polymerase II-specific; protein binding; RNA binding; RNA polymerase II cis-regulatory region sequence-specific DNA binding
Biological process: negative regulation of apoptotic signaling pathway; negative regulation of transcription by RNA polymerase II; positive regulation of cell migration; positive regulation of cell population proliferation; positive regulation of DNA-templated transcription; positive regulation of gene expression; positive regulation of phosphatidylinositol 3-kinase/protein kinase B signal transduction; termination of RNA polymerase II transcription; transcription initiation at RNA polymerase II promoter; regulation of transcription by RNA polymerase II
Cellular component: nucleoplasm; nucleus
Genetic constraint (gnomAD): Loss-of-function variants: 4 observed, 26.12 expected, observed/expected ratio (o/e) 0.15, 90% interval 0.074 to 0.35. The synonymous counts are far from expectation, so gnomAD's model fits this gene poorly and the ratio says little. Missense variants: 623 observed, 533.89 expected, observed/expected ratio (o/e) 1.17, 90% interval 1.09 to 1.25. Synonymous variants: 434 observed, 238.76 expected, observed/expected ratio (o/e) 1.82, 90% interval 1.68 to 1.95.
Homologues: Orthologues: dog MAZ (91% identical), macaque MAZ (91% identical), pig MAZ (91% identical), chimpanzee MAZ (91% identical), mouse Maz (90% identical), rat Maz (90% identical), guinea pig MAZ (76% identical), tropical clawed frog maz (48% identical), zebrafish maza (39% identical), zebrafish mazb (36% identical). Paralogues in human: VEZF1 (34% identical), PATZ1 (32% identical), ZNF143 (18% identical), ZNF281 (17% identical), ZNF76 (16% identical), PRDM10 (16% identical), MTF1 (16% identical), ZBTB16 (16% identical), ZNF148 (15% identical), ZNF384 (15% identical), PRDM1 (14% identical), ZNF362 (14% identical), and 24 more.
Diseases named in the same sentence as MAZ in open-access papers:
MAZ is named in the same sentence as 74 diseases in open-access papers, as found by Europe PMC text mining. Sharing a sentence is not in itself a finding about the gene and the disease. The quoted sentences say what the papers report.
breast carcinoma (20 papers, 2008 to 2025). "Experimental evidence suggests that MAZ expedites cell proliferation, with its overexpression linked to increased cell growth and colony formation in basal-like breast cancer (BLBC) cells." (PMID 39883338, 2024). "The Myc-associated zinc-finger protein (MAZ) was identified as participating in breast cancer cells by interacting with SAF-1 and inducing transcription of Ras." (PMID 29119102, 2017). "The deregulated expression of MYC-associated zinc finger protein (MAZ) is correlated with the progression of tumors such as colorectal adenocarcinoma, hepatocellular carcinoma, renal cell carcinoma, glioblastoma, breast carcinoma, and prostate adenocarcinoma." (PMID 37686578, 2023). "In the context of breast cancer, MAZ expression is elevated in cancer tissues compared to normal breast tissues, particularly in highly proliferative subtypes such as luminal B and HER2-enriched cancers." (PMID 39883338, 2024). "MAZ played a key role in the progression of prostate, colorectal, pancreatic, and breast cancers, among other cancers." (PMID 36890610, 2023). "The two functions of FOXF2-mediated MAZ in basic breast cancer promoted proliferation and inhibited progression." (PMID 36890610, 2023). "Analysis of TCGA data showed that SHH and MAZ were significantly overexpressed in breast cancer tissues." (PMID 36737428, 2023). "On the other hand, data from the MCF-7 human breast cancer cell line showed MAZ occupancy in the region surrounding rs34149102, which is significantly enriched for Pol II binding." (PMID 35456450, 2022). "The expression of MAZ in breast cancer tissues was significantly higher than that in adjacent normal tissues, and the survival rate of patients with high MAZ expression was significantly lower than that of patients with low expression." (PMID 35988113, 2022). "ChIP-seq data confirmed an enrichment in MAZ recruitment in the region surrounding rs34149102 in the MCF-7 breast cancer cell line." (PMID 35456450, 2022). "A breast cancer risk model consisting of 5 AS events was constructed in our study, which was risk score = (TTC39C|44853|AT*− 2.67) + (HSPBP1|52052|AP*− 4.28) + (MAZ|35942|ES*2.34) + (ANK3|11845|AP*1.18) + (ZC3HAV1|81940|AT*1.59)." (PMID 35988113, 2022). "Recently, it has been reported that expression of MAZ is elevated in many types of human cancer, such as colorectal cancer, gastric cancer, breast cancer, and prostate carcinoma." (PMID 34976812, 2021). "Regarding MAZ, a TF highly upregulated in chronic inflammatory disease and several human cancers, several studies have pointed its connection with breast cancer and colon cancer." (PMID 32850701, 2020). "For example, MAZ promoted angiogenesis through transcriptional activation of the RAS signalling pathway in breast cancer." (PMID 31488180, 2019). "MAZ promotes the tumor progression in glioblastoma, breast cancer, prostate cancer and hepatocellular cancer." (PMID 29348878, 2017). "E2A, FOXO4, NFAT and MAZ play important roles in tumor cell growth and metastasis in multiple cancers, such as colorectal cancer, breast cancer, prostate cancer and lung cancer." (PMID 29348878, 2017). "Studies have shown that deregulated expression of MAZ is closely related to the progression of tumors such as glioblastoma, breast cancer, prostate cancer and liposarcoma." (PMID 27861158, 2016). "Recent researches indicate deregulated expression of MAZ is closely related to the progression of various tumors, such as glioblastoma, breast cancer, prostate cancer and liposarcoma." (PMID 27861158, 2016). "MAZ is also known to modulate PPARgamma1 expression to promote cell growth and inhibit apoptosis in breast cancer." (PMID 27768596, 2016). "Previous report showed over-expression of MAZ in breast cancer and affected the prognosis of patients with breast cancer by up-regulating miR-34a." (PMID 27861158, 2016).
breast carcinoma (continued). "These genes were identified as putative targets of MAZ in the present study suggesting potential role for MAZ in their regulation in breast cancer cells." (PMID 19737418, 2009). "The ongoing project in our lab is to further investigate the role of MAZ in breast cancer development." (PMID 19061500, 2008). "The results revealed that down-regulation of PPARγ1 by both PPARγ and MAZ shRNAs significantly decreased cellular proliferation in MCF-7 breast cancer cells." (PMID 19061500, 2008). "Our previous studies revealed that MAZ is a critical transcriptional regulator of PPARγ1 in MCF-7 breast cancer cells." (PMID 19061500, 2008). "The biological function of MAZ was also explored in breast cancer cells." (PMID 41444950, 2025). "MAZ drove the tumor-specific expression of PPARγ1 in breast cancer cells." (PMID 36890610, 2023). "Moreover, prior studies have shown that deregulated expression of MAZ is closely related to the progression of various tumors, such as breast cancer, liposarcoma, prostate cancer, and glioblastoma." (PMID 35456450, 2022). "There is also evidence that in breast cancer, MAZ may have a dual function in regulating the development and progression of basal-like breast cancer in different stages and promote the malignant phenotypes of triple-negative breast cancer cells." (PMID 35988113, 2022). "MAZ has been reported that negatively regulate miR-34a to promote breast cancer progression." (PMID 27768596, 2016). "Furthermore, MAZ is upregulated in prostate tumors and positively regulates androgen receptor transcription, and MAZ depletion was reported to lead to reduced proliferation and increased apoptosis of prostate or breast cancer cells." (PMID 25749382, 2015). "MAZ gene locus maps on 16p11.2 and it has been found up-regulated in breast cancer." (PMID 22102859, 2011). "Also, MAZ drives tumor-specific expression of PPARG in breast cancer cells, a nuclear receptor that plays a pivotal role in breast cancer." (PMID 19737418, 2009). "This suggests that in addition to its role as a mediator of tumor-specific expression of PPARγ1, MAZ may also be involved in the regulation of other growth control genes in MCF-7 breast cancer cells." (PMID 19061500, 2008). "Therefore, expression of MAZ and its targets including miR-34a may play a pro-survival role in the context of breast cancer, and possibly of other tumours." (PMID 22102859, 2011). "In turn, high level of SAF-1/MAZ, that is present in the breast cancer cells, increases Ras gene expression allowing more SAF-1/MAZ activation by activating MAP kinase pathway." (PMID 25449683, 2015). "In the present study, we demonstrate that in breast cancer cells, constitutively activated, oncogenic ras increases DNA-binding and transcriptional activities of SAF-1/MAZ via phosphorylation through the MAP-kinase pathway." (PMID 25449683, 2015). "MAZ is known to modulate PPARgamma1 (the peroxisome proliferator-activated receptor gamma 1) and down-regulation of PPARgamma1 directly, or via down-regulation of MAZ, was shown to inhibit cell growth and to induce apoptosis in MCF-7 breast cancer cells." (PMID 22102859, 2011). "Here, we demonstrated that down-regulation of PPARγ1, directly or indirectly via knock-down of its transcriptional regulator MAZ, leads to a decrease in cellular proliferation in MCF-7 breast cancer cells." (PMID 19061500, 2008). "We identified MAZ as a transcription factor that directly binds to this promoter and drives expression of PPARγ1 in MCF-7 breast cancer cells." (PMID 19061500, 2008). "In this study, using RNA interference (RNAi) to inhibit PPARγ1 expression directly or via down-regulation of MAZ, we report for the first time that a decrease in PPARγ1 expression results in reduced cellular proliferation in MCF-7 breast cancer cells." (PMID 19061500, 2008).
breast carcinoma (continued). "Since SAF-1/MAZ is highly induced and activated in breast cancer cells and breast tumors 14 and Ras-mediated signaling pathway is highly prevalent in these tumor cells, raises the possibility of this pathway in SAF-1/MAZ activation." (PMID 25449683, 2015).
prostate carcinoma (16 papers, 2011 to 2025). A carcinoma that arises from epithelial cells of the prostate gland. "It has also been demonstrated that Myc-associated zinc finger protein (MAZ) promotes prostate cancer metastasis to the bone through transcriptional upregulation of K-RAS and subsequent activation of RALGEF and RALA." (PMID 35626682, 2022). "It was shown that the MAZ expression level was elevated in prostate cancer tissues, and its high expression was associated with the poor prognosis of prostate cancer patients." (PMID 33093444, 2020). "In prostate cancer, MAZ promotes bone metastasis through transcriptionally activating the KRas‐dependent RalGEFs pathway, and MAZ binds to the CDH1 promoter to promote epithelial‐mesenchymal transition (EMT)." (PMID 40411278, 2025). "MAZ promotes bone metastasis of prostate cancer through transcriptional promotion of the KRas/RalGEFs signal path." (PMID 36890610, 2023). "After MAZ knockout, cell proliferation was inhibited and the cell cycle was arrested in the G0/G1 phase in prostate cancer." (PMID 36988258, 2023). "Elevated expression of MAZ reported to enhance the growth and metastasis of prostate cancer by increasing the expression of androgen receptors." (PMID 36890610, 2023). "MAZ promoted prostate cancer bone metastasis by triggering transcriptional activation of the Kras-dependent RalGEFs pathway." (PMID 35903675, 2022). "Studies have reported that the expression of MAZ was upregulated in prostate cancer and that it promotes tumor progression." (PMID 34183010, 2021). "Recent studies have found that the upregulation of MAZ promotes the proliferation and metastasis of prostate cancer by promoting androgen receptor expression." (PMID 34183010, 2021). "In prostate cancer, upregulated-MAZ promotes bone metastasis through the transcriptional activation of the KRas-dependent RalGEFs pathway." (PMID 34183010, 2021). "Several studies suggest that MAZ expression is dysregulated in many types of human cancers, such as BC, colorectal cancer, gastric cancer, and prostate carcinoma." (PMID 34976812, 2021). "Theoretically, KRas mutation in this site will block the transcriptional activation of KRas by MAZ and thus affect the occurrence of bone metastasis of prostate cancer." (PMID 31488180, 2019). "When MAZ was knocked-down, cell proliferation, invasion and migration ability of prostate cancer cells were decreased." (PMID 27861158, 2016). "MAZ was also increased in prostate cancer cells and positively transcriptional regulated androgen receptor." (PMID 27861158, 2016). "Recent studies, however, reported that the MYC-associated zinc finger protein (MAZ) and the interferon regulatory factor 5 (IRF5) are direct activators of Zfp217 transcription, contributing to, respectively, prostate cancer (PCa) and pancreatic cancer aggressiveness." (PMID 36551531, 2022). "In addition, MAZ plays a key role in promotion of prostate cancer bone metastasis via transcriptional activation of the KRas/RalGEFs pathway." (PMID 34183010, 2021). "MAZ can facilitate the bone metastasis of prostate cancer via the k-ras pathway." (PMID 33093444, 2020). "MAZ also has a role in prostate cancer by interacting with the androgen receptor." (PMID 29119102, 2017). "Indeed, several lines of evidence have demonstrated that the metastatic potential of prostate cancer depends on the expression of several metastasis-related genes, or metastasis-promoting genes, which further determine the pivotal role of MAZ in bone metastasis of PCa." (PMID 31488180, 2019). "In particular, RegNetB identified the regulators PAX4, BACH1, BACH2, MAZ and TAF8 as playing a central role in this prostate cancer gene expression data set." (PMID 21682879, 2011).
neuroblastoma (13 papers, 2017 to 2025). Neuroblastoma (NB) is the most common solid, extracranial childhood tumor. "In glioblastoma, hepatocellular carcinoma, and neuroblastoma, MAZ is associated with the promotion of tumor cell migration and invasion." (PMID 40411278, 2025). "circ-CUX1 binds to Ewing Sarcoma (EWS) RBP1 (EWSR1), resulting in transactivation of MYC-associated zinc finger protein (MAZ) and inhibiting glycolysis to suppress the progression of neuroblastoma." (PMID 33425493, 2021). "For example, circCUX1 binds with EWS RNA-binding protein 1 (EWSR1) to promote its interplay with MAZ (MYC-associated zinc finger protein), glycolysis and neuroblastoma progression." (PMID 34116677, 2021). "This suggests the circCUX1/EWSR1/MAZ axis can be a therapeutic target for aerobic glycolysis and neuroblastoma progression." (PMID 35592755, 2022). "Circ‐CUX1 binds to the RRM region of EWSR1 and promotes MAZ transactivation, thereby altering the transcription of CUX1 and the association of other genes with neuroblastoma progression." (PMID 35592755, 2022). "It has been reported that circ-CUX1 binds to EWSR1 and transactivates MAZ, which contributes to aerobic glycolysis and the progression of neuroblastoma." (PMID 33425493, 2021). "The circ‐CUX1/EWSR1/MAZ axis emerges as a possible therapeutic target for neuroblastoma progression." (PMID 31709724, 2019). "Circ-CUX1 could directly bind EWSR1 and enhance its interaction with MAZ, leading to MAZ transactivation and neuroblastoma progression." (PMID 33222697, 2020). "Similarly, circ-CUX1 binds to EWS RNA-binding protein 1 (EWSR1) to promote its interaction with MYC-associated zinc finger protein (MAZ), transactivating MAZ, and modulating CUX1 expression to facilitate the metabolic reprogramming and progression of neuroblastoma (NB)." (PMID 36186139, 2022).
glioblastoma (10 papers, 2014 to 2025). The most malignant astrocytic tumor (WHO grade IV). "In addition, MAZ promoted tumor angiogenesis in human glioblastoma through transcriptional regulation of VEGF and controlled liposarcoma cell proliferation and apoptosis through directly regulating GNDF in RET signaling with synergy interaction of SPN1." (PMID 27861158, 2016). "As a ubiquitously expressed transcription factor, MAZ binds to GC‐rich cis‐elements through its C2H2‐type ZNF motif and activates transcription of KRAS and vascular endothelial growth factor (VEGF) in pancreatic cancer, cervical cancer, and glioblastoma cells." (PMID 31709724, 2019).
hepatocellular carcinoma (9 papers, 2014 to 2025). A malignant tumor that arises from hepatocytes. "It has been shown that the Myc-associated zinc finger protein (MAZ) may regulate the gene expression of Prox1 in hepatocellular carcinoma." (PMID 24503550, 2014). "However, to date, limited research has been reported for MAZ-related regulatory mechanisms, especially in hepatocellular carcinoma (HCC)." (PMID 38316778, 2024). "MAZ mutants lacking either G4 binding or phase separation ability did not form nuclear puncta, and showed deficiencies in promoting hepatocellular carcinoma cell proliferation and xenograft tumor formation." (PMID 38316778, 2024). "Interestingly, we also found that the MAZ‐2 isoform ratios of the total in GC (pan‐MAZ inhibited cell migration), papillary thyroid carcinoma (pan‐MAZ did not affect cell migration), and hepatocellular carcinoma (pan‐MAZ promoted cell migration) were 53.27%, 60.76%, and 64.54%, respectively." (PMID 40411278, 2025). "However, the role of MAZ in hepatocellular carcinoma (HCC) has not been fully elucidated." (PMID 27861158, 2016).
colorectal cancer (6 papers, 2009 to 2024). A primary or metastatic malignant neoplasm that affects the colon or rectum. "We successfully knocked down OTX2, RUNX1, MAZ,s and MAFK in HCT116 colorectal cancer cells, respectively." (PMID 35712778, 2022). "Several of the identified antigens are currently discussed as biomarkers including HSP1, MAZ, and RPS2 that are up-regulated in colorectal cancer, acute myeloid leukaemia, and astrocytoma, respectively." (PMID 19284601, 2009).